VEGFA (vascular endothelial growth factor A)
Diseases named in the same sentence as VEGFA in open-access papers (continued):
Sharing a sentence is not in itself a finding about the gene and the disease.
gastric cancer (continued). "As for gastric cancer resistance, miR-613 prevents NUTM2A-AS1-induced resistance of gastric cancer cells to bitter ginseng alkaloids, a process achieved by affecting oxidative stress-related ROS production, glutathione levels, and SOD activity, subsequently adjusting the expression levels of VEGFA." (PMID 40028033, 2025). "In gastric cancer (GC), activation of JAK2/STAT3 could promote HIF-1α/VEGFA axis, and bolsters macrophage polarization, thus facilitating GC metastasis and angiogenesis." (PMID 39130627, 2024). "Additionally, METTL3 could promote angiogenesis and metastasis in gastric cancer (GC) and bladder cancer through regulating m6A and mRNA stability of hepatoma-derived growth factor (HDGF), tyrosine kinase endothelial (TEK) and VEGFA, respectively." (PMID 38322265, 2024). "Has-miR-302a-3p overexpression reduces the expansion of the stomach cancer cell line SGC-7901 and promotes apoptosis by targeting the negative control of VEGFA (vascular endothelial growth factor A) expression." (PMID 38329551, 2024).
hepatocellular carcinoma (593 papers, 2008 to 2026). A malignant tumor that arises from hepatocytes. "We assessed these genes in the HCCDB database, VEGFA is not only clearly associated with hepatocellular carcinoma prognosis, but is primarily secreted by malignant cells." (PMID 40316995, 2025). "High VEGFA expression is also associated with decreased tumor-infiltrating lymphocytes and poorer prognosis in hepatocellular carcinoma patients." (PMID 39006665, 2024). "Similarly, the enhancement of EGFR and VEGFA translation in lenvatinib‐resistant hepatocellular cancer has been linked to METTL1 activity." (PMID 39979979, 2025). "Among these candidate genes, transcription factor Zinc Finger Homeobox 3 (ZFHX3) is known to mediate hypoxia-induced angiogenesis in hepatocellular carcinoma via transcriptional activation of VEGFA." (PMID 41543887, 2026). "In hepatocellular carcinoma, m6A methylation of vascular endothelial growth factor A (VEGFA) mRNA was modified by methyltransferase RBM15 and two readers, YTHDF2 and IGF2BP3." (PMID 41272900, 2025). "We reversed the effects of FTO on VEGFA expression in hepatocellular carcinoma cells through VEGFA siRNA or plasmids." (PMID 40316995, 2025). "Pathological angiogenesis linked to VEGFA plays a significant role in the progression of NAFLD, fostering inflammation, fibrosis, and development of hepatocellular carcinoma." (PMID 39081807, 2024). "In hepatocellular carcinoma, METTL1/WDR4-mediated m7G tRNA modification significantly promotes the translation of cyclin A2, EGFR, and VEGFA, promoting the spread and metastasis of hepatocellular carcinoma cells." (PMID 39019857, 2024). "The discovery that BMP9-ID1 can activate the expression of HIF-1α and VEGFA supports a new strategy for developing targeted therapies for hepatocellular carcinoma." (PMID 39619441, 2024). "In hepatocellular carcinoma, increased VEGFA expression promotes the expression of PD-1, CTLA-4 and Tim-3 on T cells, as well as inhibits the secretion of interferon γ (IFNG) and granulosase B." (PMID 38687357, 2024). "Hsa-miR-205-5p was found to be a key regulator of VEGFA during cancer-related angiogenesis in hepatocellular carcinoma." (PMID 38132183, 2023). "Here the authors report that low-dose radiotherapy enhances the antitumor effect of dual VEGFA and PD-L1 blockade in preclinical models of hepatocellular carcinoma." (PMID 38001101, 2023). "Some miRNAs can regulate the vascular endothelial growth factor A (VEGFA) gene, which acts in blood vessel growth in some cancer types, including hepatocellular carcinoma." (PMID 35205327, 2022). "Hepatoma cell-derived exosomes carrying miR-296 regulated EAG1/VEGFA pathway, affecting the tube-forming ability of cells." (PMID 36230535, 2022). "This miRNA was previously noted to regulate vascular endothelial growth factor A (VEGFA) expression in liver cirrhosis and hepatocellular carcinoma." (PMID 33807742, 2021). "Analogously, the PIK3C2α/AKT/HIF-1α/VEGFA pathway regulated by miR-26a plays a role in inhibiting angiogenesis in hepatocellular carcinoma." (PMID 32014012, 2020). "Experimental validated miRNA : VEGFA mRNA interactions were found for miR-20a-5p and miR-20b-5p, and in hepatocellular carcinoma for miR-381-3p." (PMID 32848728, 2020). "In particular, cerebral HRMs, such as miRNA-195-5p and miRNA-451a, have been both reported to suppress vascular endothelial growth factor A (VEGF-A) levels, thereby reducing new vessel formation in hepatocellular carcinoma in a rat brain after stroke." (PMID 33076256, 2020). "IL-6 promotes angiogenesis via IL-6/STAT3/VEGFA signaling in hepatocellular carcinoma, cervical cancer, and glioma carcinoma cells." (PMID 32993787, 2020). "LncRNA UBE2CP3 promotes angiogenesis in hepatocellular carcinoma cells by activating ERK/HIF-1α/VEGFA signaling." (PMID 32993787, 2020).
hepatocellular carcinoma (continued). "Chai and co-workers detected that expression of VEGF-A was inversely correlated with miR-26a-5p expression in hepatocellular carcinoma and that miR-26a-5p modulated angiogenesis of hepatocellular carcinoma through the PIK3C2α/Akt/HIF-1α/VEGFA pathway." (PMID 29483572, 2018). "CBX3 has been previously identified as a potential biomarker for tumor stem cells in osteosarcoma, while CBX4 has been reported to induce hypoxia-mediated activation of VEGFA (vascular endothelial growth factor A) and angiogenesis in hepatocellular carcinomas." (PMID 28851357, 2017). "Further, in hepatocellular carcinoma, upregulation of miR-125a significantly repressed the expression of vascular endothelial growth factor A (VEGF-A) and matrix metalloproteinase 11 (MMP11), both in vitro and in vivo." (PMID 25093848, 2014). "Angiogenesis is a hallmark of hepatocellular carcinoma (HCC), yet most cases resist antiangiogenic drugs (AADs) targeting VEGFA-VEGFR2, and the molecular mechanisms remain largely unknown." (PMID 41760604, 2026). "Combination therapy with the anti–programmed death-ligand 1 (anti-PD-L1) antibody atezolizumab and the anti–vascular endothelial growth factor-A (anti-VEGF-A) antibody bevacizumab (Atezolizumab/Bevacizumab) has commonly been used as first-line treatment for advanced hepatocellular carcinoma (HCC)." (PMID 41140754, 2026). "Additionally, it plays a role in promoting hepatocellular carcinoma via the miR-203b/VEGFA axis and contributes to the progression of bladder cancer by modulating the Wnt3a/β-Catenin signaling pathway." (PMID 38279317, 2024). "Studies conducted in hepatocellular carcinoma (HCC) reported that patients with VEGFA amplification were particularly responsive to VEGFA-targeted therapy, and sorafenib specifically, suggesting that it can be used as a predictive biomarker for personalized treatment of HCC with sorafenib." (PMID 37893095, 2023). "Furthermore, circUSP25 (hsa_circ_0001178) can induce hepatocellular carcinoma progression by regulating the miR-382/VEGFA axis." (PMID 36006268, 2022). "Additionally, OIP5-AS1 acts as a ceRNA by binding to miR-3163 to up-regulate VEGFA expression in hepatocellular carcinoma." (PMID 35602889, 2022). "VEGFA can induce proliferation and activation of HSCs and metastasis of cancer cells, stimulate neovascularization and extracellular matrix production, and facilitate progression of liver fibrosis and hepatocellular carcinoma development." (PMID 35707473, 2022). "Reduction in miR-205-5p expression and subsequent inadequate suppression of VEGFA lead to excessive activation of VEGF signaling and neovascularization in hepatocellular carcinoma and bladder cancer, among others, and these events are critical for tumor growth and spread." (PMID 34370714, 2021). "Among these, Hep3B human hepatoma cells exhibited the highest levels of VEGFA." (PMID 32131390, 2020). "Atezolizumab (anti-PD-L1) combined with bevacizumab (anti-VEGFA) is the first-line immunotherapy for advanced hepatocellular carcinoma (HCC), but the number of patients who benefit from this regimen remains limited." (PMID 38001101, 2023). "The study goal was to examine VEGFA (vascular endothelial growth factor A) expression in hepatocellular carcinoma (HCC) cell lines upon transfection miR-612, miR-637, or miR-874." (PMID 35205327, 2022). "Hepatocellular carcinoma (HCC) cells were sensitized to regorafenib through the inhibition of the expression of both vascular endothelial growth factor A (VEGF-A) and myeloid cell leukemia 1 (MCL-1) by siRNA." (PMID 33922992, 2021). "Hepatocellular carcinoma (HCC)-associated long noncoding RNA (HANR) promotes lymphangiogenesis of HCC by secreting miR-296-enriched EVs and regulating EAG1/VEGFA signaling in human skin LECs." (PMID 34552874, 2021).
hepatocellular carcinoma (continued). "Studies have shown that SRI regulates VEGFA/B expression via the PI3K pathway and negatively modulates pyroptosis by interacting with the NLRP3 inflammasome, thereby promoting hepatocellular carcinoma proliferation." (PMID 40228435, 2025). "Excessive activation of RAS/MAPK signaling is commonly observed in hepatocellular carcinoma (HCC), and it has been found that RIT1 induces angiogenesis through the MEK/ERK/EIF4E/HIF1-α/VEGFA axis." (PMID 36941564, 2023). "The inhibition of miR-125a-5p in hepatocellular cancer patients increased the expression of MMP11 and the vascular endothelial growth factor A (VEGFA) protein." (PMID 36359429, 2022). "In hepatocellular carcinomas, miR-503 inhibited tumor angiogenesis by down-regulation of FGF2 and VEGFA." (PMID 33762949, 2021). "We concluded that IGF1, VEGFA, and SERPINE1 had statistical significance in the expression and 10-year survival rate between hepatocellular carcinoma group and normal group." (PMID 33960267, 2021). "HDAC6 promotes cell proliferation of hepatocellular carcinoma and HIF-1α and VEGFA expression, thereby promoting HIF-1-mediated angiogenesis in hypoxic conditions." (PMID 33109235, 2020). "In another study in hepatocellular carcinoma, FOXC1 knockdown led to a downregulation of the pro-angiogenic factor VEGFA, consistent with the developmental roles of FOXC1 as a VEGF-responsive mediator of blood vessel formation." (PMID 30764547, 2019). "Furthermore, high miR‐18a expression was correlated with a high recurrence rate in hepatocellular carcinoma (HCC) by promoting pathological angiogenesis via an increase in VEGFA expression." (PMID 29266846, 2018). "In addition to the finding that ERO1α deficiency can inhibit angiogenesis by increasing N-glycosylation of VEGFA, ERO1α also induces the S1PR1/STAT3/VEGF-A signaling pathway triggers tumor migration, angiogenesis, invasion, and EMT of hepatocellular carcinoma." (PMID 41333024, 2025). "In vitro studies of hepatocellular carcinoma found a positive correlation between YY1 and VEGFA." (PMID 41327312, 2025). "Recently, a study performed on hepatocellular carcinoma showed that inhibition with miR-874-3p did not reduce the expression of the VEGFA at the mRNA level, but reduced protein expression at a certain extent." (PMID 35806488, 2022). "In hepatocellular carcinoma (HCC), the upregulated fatty acid-binding protein 1 (FABP1) interacts with the VEGF receptor and Src via the focal adhesion kinase (FAK) and enhances the expression of the angiogenic vascular endothelial growth factor A (VEGF-A)." (PMID 34685761, 2021). "Another study showed that VEGFA rs25648 (−73C > T) was a prognostic biomarker for PFS and OS in patients with hepatocellular carcinoma, with C-allele conferring improved prognosis, despite not confirmed in multivariate analysis." (PMID 33353148, 2020). "In addition to VEGFA, we demonstrated that hypoxia, a condition increasing VEGFA expression, also upregulates FABP4 as well as in hepatoma cell lines." (PMID 30575815, 2019). "Additionally, miR-503 also represses hepatocellular carcinoma tumor angiogenesis by targeting the potent angiogenic factors FGF2 and VEGFA." (PMID 25653011, 2015). "miR-503 was found underexpressed in hepatocellular carcinoma (HCC) and was shown to inhibit angiogenesis in vitro and in vivo by downregulating expression of both fibroblast growth factor 2 (FGF2) and vascular growth factor A (VEGFA)." (PMID 26834703, 2015). "Malignant tumors including ovarian cancer (OC), non-small cell lung cancer (NSCLC), and hepatocellular carcinoma (HCC) are known to have tumor vascularization that is connected to over- stimulation of platelet-derived growth factor (PDGF) signaling, either alone or in conjunction with VEGFA." (PMID 41334166, 2025).
hepatocellular carcinoma (continued). "Additionally, it has been found miR-199a/b-3p can inhibit HCC growth, apoptosis, invasion and angiogenesis via multiple targets, such as PDCD4, CD44, CD151, VEGFA AEGFR1/2, HGF and MMP235–38 and can affect the chemical sensitivity of hepatoma cells to doxorubicin via mTOR and c-Met39." (PMID 38168113, 2024). "In addition, VEGFA-induced HCC development and pathogenesis may be a potential pharmacological target for treating hepatocellular carcinoma." (PMID 34603055, 2021). "In hepatocellular carcinoma cells, overexpressed lncRNA UBE2CP3 enhances human umbilical vein endothelial cell proliferation, migration and angiogenesis, which is attributed to the ERK/p70S6K/HIF-1α/VEGFA signaling axis activated by lncRNA expression deviating from normal status." (PMID 32014012, 2020). "However, in another study, it was found that knockdown of HDAC6 significantly upregulated the expression of HIF-1α and VEGFA in vivo and in vitro and promoted HIF-1α-mediated hepatocellular carcinoma (HCC) angiogenesis." (PMID 40260239, 2025). "Vascular endothelial growth factor A (VEGFA) is an important angiogenesis regulator, which plays an important role in angiogenesis and progression of tumor, including hepatocellular carcinoma (HCC)." (PMID 28147320, 2017). "The aims of this study were to investigate whether miR-26a inhibited angiogenesis by down-regulating vascular endothelial growth factor A (VEGFA) and its clinical relevance in hepatocellular carcinoma (HCC)." (PMID 24194905, 2013). "Irradiation significantly upregulated the mRNA expressions of FasL, TRAIL, TNF-α, and TGF-β1 in hepatoma cells, and downregulated the mRNA expressions of IGF-1 and PDGFB, but no obvious effects on the expressions of VEGFA, PDGFA, and IL-6." (PMID 27431384, 2016).
macular edema (559 papers, 2007 to 2026). "Retinal ischemia drives the production of cytokines, such as vascular endothelial growth factor-A (VEGF-A), which increase vascular permeability resulting in an accumulation of fluid in the macular edema) and subsequent vision loss." (PMID 37175621, 2023). "Vasoactive growth factors and inflammatory cytokines, including vascular endothelial growth factor-A (VEGF) and tumor necrosis factor (TNF)-α, are upregulated in the ocular fluids in macular edema and have been implicated in disruption of the BRB." (PMID 36960343, 2023). "The analysis of the serum of PDR patients, treated with intravitreal injection of aflibercept, highlighted that only VEGFA levels were modified, along with the resolution of the macular edema." (PMID 33334029, 2020). "Additionally, we concentrated on several genes presumed to play a role in the pathophysiology of macular edema: VEGFA, VEGFC, EPO, NOS3 (eNOS), PLVAP, and APOE4." (PMID 40455044, 2025). "In addition, VEGFA is responsible for ED, angiogenesis, vascular permeability, and macular edema by stimulating ECs through a protein kinase C (PKC)-dependent mechanism that subsequently enhances retinal and glomerular permeability." (PMID 36982499, 2023). "The aim of this study was to report the successful use of ranibizumab, an antibody raised against human vascular endothelial growth factor A (VEGF-A), in fingolimod-associated macular edema (FAME) and to provide a detailed review about this adverse event with emphasis on diabetic MS patients." (PMID 27983657, 2016). "Hence, it is likely that the proinflammatory CD14++ MC may promote angiogenesis and macular edema with up-regulated VEGFA-VEGFR2 pathway." (PMID 34594230, 2021).
colon carcinoma (555 papers, 2001 to 2025). "We observed that the regulatory mechanism of the miR-152-3p/PVT1/VEGFA axis causes metastasis in colon cancer through the overexpression and inhibition of miR-152-3p in colon cells." (PMID 34336125, 2021). "Computational analysis was performed to determine genes associated with the exosomal long noncoding (lncRNA) plasmacytoma variant translocation 1 (PVT1)/vascular endothelial growth factor A (VEGFA) axis in patients with colon cancer." (PMID 34336125, 2021). "Previous studies have indicated that polymorphisms in CASP3 and CASP8 are related to colon cancer, and the VEGFA was also significantly associated with rectal cancer." (PMID 33101392, 2020). "This study is significant since it has been shown that expression of VEGFA is increased in colon cancer and is associated with disease localization, stage and long-term disease-specific survival." (PMID 23536895, 2013). "Upregulation of miR-192–5p has also been found to play a role in inhibiting metastatic potential of colon cancer by downregulating expression of Bcl-2, Zeb2 and VEGFA, factors that inhibit apoptosis and promote cell growth." (PMID 40777372, 2025). "Colon cancer cells can express high levels of VEGFA and bFGF and promote angiogenesis through their paracrine effects." (PMID 40515512, 2025). "Our study showed that PKN2 inhibited the expression and secretion of VEGFA and bFGF by colon cancer cells." (PMID 40515512, 2025). "Through qRT-PCR testing, we observed that in colon cancer tissue, the mRNA expression levels of VEGFA (p < 0.05), TIMP1 (p < 0.0001), MYC (p < 0.0001), and EPHA2 (p < 0.05) were higher than in normal tissue." (PMID 38773226, 2024). "Other studies have found that the CXC chemokine-VEGFA network is significantly correlated with immune cell infiltration in colon cancer." (PMID 38687357, 2024). "Before we started, we detected the expression levels of MMP3, MMP9, TIMP1, VEGFA in various colon cancer cell lines by qRT-PCR assay, and found that these genes were highly expressed in RKO and SW480, and we chose RKO and SW480 for the following experiments." (PMID 39177661, 2024). "Evidence of VEGFA as the sole MR unique to Cubisbel potentially suggests a clinical advantage for the combination of Cubisbel with targeted anti-VEGF therapies routinely used to treat colon cancer such as bevacizumab." (PMID 37934338, 2024). "It has been reported that bLF suppresses lung or colon cancer growth through decreasing the expression of VEGFA and pro-inflammatory cytokines." (PMID 36678795, 2023). "These reduced expression levels of LGR5 and RSPO3 occurred in parallel with reduced expression levels of unphosphorylated (active) β-catenin and its downstream target VEGFA in colon cancer cells." (PMID 37998393, 2023). "To further validate our findings, we investigated how Foxy5 treatment affected VEGFA mRNA and protein levels in colon cancer tissues from a xenograft mouse model." (PMID 37998393, 2023). "This inhibits stemness and VEGFA expression, suggesting novel treatment strategies for the drug candidate Foxy5 in the handling of colon cancer patients." (PMID 37998393, 2023). "For example, in colon cancer, cytoskeleton protein 4.1 regulates the secretion and expression of VEGFA, which affects the proliferation, migration, angiogenesis, and invasion of colon cancer cells." (PMID 36835189, 2023). "The miRNA miR-150-5p has been found to suppress tumor progression by targeting VEGFA in colon cancer." (PMID 35053577, 2022). "For example, miR-299-3p acted as a tumor suppressor, inhibiting cell proliferation and invasion and inducing apoptosis by downregulation of OCT4 or VEGFA expression in renal and colon carcinoma, respectively." (PMID 33817318, 2021). "Exosomal PVT1 promotes colon cancer metastasis through its association with EGFR and VEGFA expression." (PMID 34336125, 2021).